CALCR (calcitonin receptor)
Description:
G protein-coupled receptor activated by ligand peptides amylin (IAPP), calcitonin (CT/CALCA) and calcitonin gene-related peptide type 1 (CGRP1/CALCA). CALCR interacts with receptor-activity-modifying proteins RAMP1, 2 and 3 to form receptor complexes AMYR1, 2 and 3, respectively. IAPP, CT and CGRP1 activate CALCR and AMYRs with distinct modes of receptor activation resulting in specific phenotypes. Ligand binding causes a conformation change that triggers signaling via guanine nucleotide-binding proteins (G proteins) and modulates the activity of downstream effectors. Activates cAMP-dependent pathway. [Isoform 2]: Non-functional protein. Unable to couple to G proteins and activate adenylyl cyclase. Does not undergo receptor internalization following ligand binding.
Synonyms: CT-R; CTR; CRT; CTR1
Tractability: Small molecule: a structure with a bound ligand is known; a high-quality ligand is known; it belongs to a druggable protein family. Antibody: UniProt places it where antibodies can reach, with high confidence; its Gene Ontology location is reachable by antibodies, with high confidence; UniProt predicts a signal peptide or a membrane-spanning region. PROTAC: a small molecule that binds it is known. Other modalities: an approved drug acts on it.
Target class: Calcitonin-like receptor; Peptide receptor (family B GPCR); Family B G protein-coupled receptor; Membrane receptor; Calcitonin receptor
Gene: Protein-coding gene on chromosome 7 (93,424,486 to 93,575,738, reverse strand). Ensembl gene ENSG00000004948.
Subcellular location: Cell membrane
Subcellular location (Human Protein Atlas): Cell Junctions; Centriolar satellite; Vesicles
Pathways (Reactome):
Signal Transduction: Calcitonin-like ligand receptors; G alpha (s) signalling events
Gene Ontology:
Molecular function: amylin receptor activity; amyloid-beta binding; calcitonin binding; calcitonin family receptor activity; calcitonin gene-related peptide receptor activity; calcitonin receptor activity; protein binding; G protein-coupled receptor activity; transmembrane signaling receptor activity
Biological process: adenylate cyclase-activating G protein-coupled receptor signaling pathway; amylin receptor 1 signaling pathway; amylin receptor 2 signaling pathway; amylin receptor 3 signaling pathway; amylin receptor signaling pathway; calcitonin family receptor signaling pathway; positive regulation of calcium-mediated signaling; positive regulation of cAMP/PKA signal transduction; positive regulation of ERK1 and ERK2 cascade; positive regulation of gene expression; positive regulation of phosphatidylinositol 3-kinase/protein kinase B signal transduction; response to amyloid-beta; response to glucocorticoid; positive regulation of cytosolic calcium ion concentration; cell surface receptor signaling pathway; G protein-coupled receptor signaling pathway
Cellular component: amylin receptor complex 1; amylin receptor complex 2; amylin receptor complex 3; plasma membrane; axon; acrosomal vesicle; cilium; membrane
Genetic constraint (gnomAD): Loss-of-function variants: 23 observed, 31.36 expected, observed/expected ratio (o/e) 0.73, 90% interval 0.53 to 1.04. The upper end of that interval is the gene's LOEUF score, 1.04, which puts it in group 4 of 6, group 1 being the genes least tolerant of losing a copy. Missense variants: 345 observed, 390.07 expected, observed/expected ratio (o/e) 0.88, 90% interval 0.81 to 0.97. Synonymous variants: 147 observed, 144.11 expected, observed/expected ratio (o/e) 1.02, 90% interval 0.89 to 1.17.
Homologues: Orthologues: chimpanzee CALCR (99% identical), macaque CALCR (96% identical), rabbit CALCR (88% identical), dog CALCR (88% identical), guinea pig CALCR (87% identical), rat Calcr (80% identical), mouse Calcr (78% identical), pig CALCR (73% identical), zebrafish calcr (59% identical), tropical clawed frog calcr (58% identical). Paralogues in human: CALCRL (53% identical), PTH1R (29% identical), PTH2R (28% identical), VIPR1 (27% identical), ADCYAP1R1 (26% identical), SCTR (25% identical), GIPR (25% identical), GCGR (24% identical), GLP1R (24% identical), GHRHR (24% identical), GLP2R (23% identical), VIPR2 (23% identical), and 30 more.
Diseases named in the same sentence as CALCR in open-access papers:
CALCR is named in the same sentence as 77 diseases in open-access papers, as found by Europe PMC text mining. Sharing a sentence is not in itself a finding about the gene and the disease. The quoted sentences say what the papers report.
osteoporosis (16 papers, 2009 to 2026). A condition of reduced bone mass, with decreased cortical thickness and a decrease in the number and size of the trabeculae of cancellous bone (but normal chemical composition), resulting in increased fracture incidence. "More genes like interleukin 6 (IL-6), vitamin D receptor (VDR), estrogen receptor (ESR), and calcitonin receptor (CTR) as well others were suggested to be associated with osteoporosis and bone density." (PMID 34938374, 2021). "The calcitonin receptor mediates calcium homeostasis, bone mineral density by osteoclast-mediated bone resorption, and its dysfunction is associated with osteoporosis." (PMID 31091839, 2019). "CALCR (the calcitonin receptor) has been associated with osteoporosis in humans." (PMID 28861242, 2017). "Missense mutations in ADRB2, CNR2, FSHR, TSHR, CALCR, and GIPR genes were earlier associated with decreased BMD and osteoporosis in postmenopausal women as leading to amino acid substitutions and the possible receptor structure and/or function change." (PMID 39769358, 2024). "Up till now, tens of hundreds of risk genes have been identified for osteoporosis, including collagen type I α 1 gene (COL1A1), calcitonin receptor (CTR), estrogen receptor (ESR), vitamin D receptor (VDR), and so on." (PMID 32627819, 2020). "The polymorphisms of CALCR were related to human BMD and played a role during the pathogenesis of osteoporosis." (PMID 19284518, 2009). "We found specific osteoporosis-linked SNPs in genes encoding key receptors involved in bone metabolism that are classified into rhodopsin (ADRB2, CNR2, MTNR1B, FSHR, TSHR, LGR4), secretin (CALCR, GIPR), and other T7M (WLS) receptor families." (PMID 39769358, 2024). "Calcitonin receptor (CTR) is a class B G protein-coupled receptor (GPCR) that regulates calcium homeostasis and bone turnover upon activation by calcitonin and is an osteoporosis drug target." (PMID 39188952, 2024).
Obesity (9 papers, 2017 to 2025). Accumulation of substantial excess body fat. "Nevertheless, these few trials with davalintide illustrate how the calcitonin receptor system may constitute a target for the treatment of obesity and associated metabolic conditions such as NAFLD." (PMID 33488526, 2020). "In this study, we investigated the add-on potential of the dual amylin and calcitonin receptor agonist (DACRA) KBP-089 in combination with the GLP-1 receptor agonist liraglutide as obesity treatment in high-fat diet (HFD) fed rats." (PMID 33413317, 2021). "Nevertheless, salmon calcitonin, like new compounds such as long-acting amylin analogues and DACRAs, demonstrates a potential for combined amylin and calcitonin receptor agonism as a future treatment strategy for obesity and related conditions such as NAFLD." (PMID 33488526, 2020). "AmyR consist of a calcitonin receptor (CTR) associated with a receptor activity-modifying protein, and some ligands activate both AmyR and CTR, which has generated interest in dual amylin/calcitonin receptor agonists (DACRAs) for obesity treatment." (PMID 39389183, 2025). "Although we used molecular profiling to identify potential targets for the treatment of obesity, the approach we developed to identify Hcrtr1 and CalcR as drug targets is general and could be applied to other neurologic disorders." (PMID 36411386, 2022). "The significant genes in GWAS results (CALCR, PLAG1, INSIG2, PPARG, BMP5, S100A10) also have been identified to have relationship with growth performance and obesity of adipose tissue for pig and cattle." (PMID 33264312, 2020). "The human POMC cluster C4-374, corresponding to the mouse Glp1r-expressing POMC neurons, instead expresses the calcitonin receptor (CALCR), highlighting the interspecies heterogeneity of POMC populations, which has direct implications for currently licensed obesity therapies." (PMID 39910307, 2025).
breast carcinoma (7 papers, 2017 to 2024). "Real-time quantitative PCR validation of RNA-seq data was done for IDH2, ID1, KRT80, and CALCR genes both in circNFATC3 silenced MDA-MB-231 breast cancer cells and SK-OV-3 ovarian cancer cells." (PMID 33816459, 2021). "Moreover, CALCR is also found to be expressed in a number of cancer cell lines such as breast cancer, bone cancer, prostate cancer, multiple myeloma, leukemia and glioblastoma." (PMID 38985127, 2024). "The induction of miR-489 mainly occurred at the transcriptional level because the mRNA levels of its host gene, CALCR, were increased in several ER-positive breast cancer cell lines upon estrogen treatment and correlated with miR-489 expression levels in breast cancers." (PMID 35897675, 2022). "However, the induction of CALCR gene expression was more robust than the induction of miR-489 in the ER+ breast cancer cell lines MCF7 and T47D, indicating that additional regulatory mechanisms may be involved." (PMID 35897675, 2022). "Therefore, MAD2L1, RSL1D1, and CALCR might be promising candidates for further research in endocrine therapy-resistant breast cancer as potential therapeutic targets or prognostic markers." (PMID 33133141, 2020). "To examine this hypothesis, we stimulated three ER+ breast cancer cell lines (T47D, MCF7, and BT474) with estrogen or ethanol for indicated time periods and measured the expression of miR-489 and its host gene, CALCR." (PMID 35897675, 2022). "CALCR (coding calcitonin receptor) has similar gene expression patterns to MAD2L1 and RSL1D1 in tamoxifen-resistant MCF7 cells; the expression of these genes was all correlated with worse RFS in ER-positive/HER2-negative breast cancer patients who had undergone endocrine therapies only." (PMID 33133141, 2020).
migraine (7 papers, 2020 to 2024). "This activation, in turn, influences other proteins like RAMP 1–3, CALCB, CALCR, and SLC5A2, which are implicated in migraine attacks." (PMID 39215033, 2024). "OPRM1 emerges as a pivotal hub, instigating the activation of GNAS and GNB1, subsequently influencing proteins such as RAMP1, RAMP2, RAMP3, CALCB, CALCR, and SLC5A2 all implicated in migraine attacks." (PMID 39215033, 2024). "Calcitonin receptor (CTR)-based receptors, such as the amylin 1 (AMY1) receptor, and ligands, calcitonin gene-related peptide (CGRP) and amylin, have been linked to migraine and pain." (PMID 38481170, 2024). "RAMP1 belongs to the receptor activity-modifying protein (RAMP) family, best known for its role in modulating the activity of the calcitonin receptor (CLR), which has significant implications in the treatment of migraines." (PMID 39188714, 2024).
prostate carcinoma (7 papers, 2016 to 2024). A carcinoma that arises from epithelial cells of the prostate gland. "However, there is evidence that calcitonin can increase CD44 variant RNA and protein levels via p38 pathway in CALCR-positive prostate cancer cell." (PMID 38985127, 2024). "Conversely, in PC3 prostate cancer cells, CALCR promoted proliferation and invasion while suppressing apoptosis through its interaction with zonula occludens-1 and inducing PKA-mediated disassembly of tight junctions." (PMID 38985127, 2024). "Recently calcitonin and calcitonin receptor (CTR) have been demonstrated to be highly expressed in advanced grades of prostate carcinoma; calcitonin and CTR are supposed to be involved in a favourable paracrine axis able to induce the progression from a localized to a metastatic cancer." (PMID 28044110, 2016).
glioblastoma (6 papers, 2016 to 2025). The most malignant astrocytic tumor (WHO grade IV). "Some studies have shown that the expression of CALCR is increased in neuroendocrine tumors and chronic pancreatitis, and it may inhibit the progression of glioblastoma through the CT-CALCR signal axis." (PMID 35252217, 2021). "CALCR expression has been identified in several cancer cell lines, including those derived from BC, PC, bone cancer, multiple myeloma, leukemia (LKM) and glioblastoma (GBM)." (PMID 39859313, 2025).
glioma (6 papers, 2016 to 2025). A benign or malignant brain and spinal cord tumor that arises from glial cells (astrocytes, oligodendrocytes, ependymal cells). "For instance, it has been observed that somatic mutations in the CALCR gene led to a loss of the function of the protein in glioma cells, which correlated with a poor prognosis." (PMID 38542389, 2024). "In another study, SO1861 was combined with chemical conjugates of dianthin-30 and a monoclonal anti-calcitonin receptor antibody and tested on high-grade glioma cell lines SB2b, JK2 and U87MG, resulting in IC50 values of 0.01 nM, 0.01 nM and 0.02 nM." (PMID 31614697, 2019). "In this study we tested expression and performed pharmacological characterization of the calcitonin receptor (CTR) as well as other members of the calcitonin family of receptors in high-grade glioma (HGG) cell lines derived from individual patient tumours, cultured in defined conditions." (PMID 30777055, 2019). "In contrast, TUBA1B-low-expressing Glioma cells mainly transmitted signals through the PTN pathway and received signals via the PTN, MK, EGF, and CALCR pathways." (PMID 40094001, 2025).
kidney stone (3 papers, 2014 to 2021). "Several polymorphisms of the CALCR and CASR genes were also associated with recurrent kidney stones." (PMID 33956883, 2021).
leukemia (3 papers, 2005 to 2025). A malignant (clonal) hematologic disorder, involving hematopoietic stem cells and characterized by the presence of primitive or atypical myeloid or lymphoid cells in the bone marrow and the blood. "Our data also suggest that the mechanism whereby hERG1 channels stimulate secretion depends on a modulation at the mRNA level, similarly to what we have previously reported in leukaemia cells for the calcitonin receptor." (PMID 16175187, 2005). "Another notable example of highly context-specific co-regulation of signaling axes is the one mediated by CALCR and its close paralog, CALCRL, whose interaction with ADM is a critical factor determining relapse and drug resistance in leukemia." (PMID 38723607, 2024).
osteoarthritis (3 papers, 2011 to 2026). A noninflammatory degenerative joint disease occurring chiefly in older persons, characterized by degeneration of the articular cartilage, hypertrophy of bone at the margins and changes in the synovial membrane. "Thus there are several indications that modulation of the calcitonin receptor (CTR) is a valid target for treatment of joint degenerative diseases." (PMID 21996094, 2011).
ovarian carcinoma (3 papers, 2021 to 2023). A malignant neoplasm originating from the surface ovarian epithelium. "Another example is an epitope in an out-of-frame ORF in CALCR—a Calcitonin receptor gene—in ovarian cancer (KVFGLNILK), that had a high MHC-I binding affinity (8.91 nM) and was conserved in five species." (PMID 37275273, 2023).
Alzheimer disease (2 papers, 2021 to 2024). A progressive, neurodegenerative disease characterized by loss of function and death of nerve cells in several areas of the brain leading to loss of cognitive function such as memory and language. "Recent studies have brought attention to the activation of the calcitonin receptor through the calcitonin gene-related peptide (CGRP), revealing the potential therapeutic effects of calcitonin in Alzheimer’s disease (AD) and metabolic syndrome (MetS)." (PMID 38809924, 2024).
coronary artery disease (2 papers, 2019 to 2026). "In our study, rs2870463 G in CTRB1 gene was associated with decreased birthweight and increased risk of coronary artery disease with posterior probability (PP) = 0.951 and rs12704673 T in CALCR gene was associated with increased birthweight and increased waist circumference with PP = 0.962." (PMID 30858448, 2019). "Two novel loci were associated with birthweight and adult coronary artery disease (rs2870463 in CTRB1) and with birthweight and adult waist circumference (rs12704673 in CALCR)." (PMID 30858448, 2019).
encephalitis (2 papers, 2012 to 2016). An acute inflammatory process affecting the brain parenchyma. "Other studies have also discovered loci on mouse chromosome 16 associated with mortality, mouse chromosome 12 which was associated with weight loss, CD45 tyrosine phosphatase (protective immunity against encephalitis), and the calcitonin receptor which was related to susceptibility to encephalitis." (PMID 26962864, 2016).
urolithiasis (2 papers, 2019 to 2021). Stone(s) within the urinary tract. "In adult urolithiasis, significantly increased risk of calcium stone urolithiasis was also found in CALCR rs1801197 in allelic comparison (T vs. C)." (PMID 31626518, 2019). "In pediatric urolithiasis subgroup and overall, significantly increased risk of calcium stone urolithiasis was found in CALCR rs1801197 in all genetic models." (PMID 31626518, 2019). "In adult urolithiasis and its male subgroup, significantly increased risk of calcium stone urolithiasis was found in CALCR rs1801197 in heterozygote comparison (CT vs. CC) and dominant model (CT+TT vs. CC)." (PMID 31626518, 2019). "There is insufficient data to fully confirm the association between CALCR rs1801197 and calcium stone urolithiasis susceptibility in pediatric urolithiasis, adult urolithiasis, adult recurrent urolithiasis subgroup and gender subgroup, and the results should be interpreted with caution." (PMID 31626518, 2019). "The association between the CASR, CALCR, and ORAI1 genes polymorphisms and the urolithiasis development has been shown in a number of studies conducted in Italian, Indian, and Iranian, Chinece populations by different researchers." (PMID 34054913, 2021). "In adult urolithiasis and its male subgroup, when study NO 1.4 or 1.5 was excluded, statistically different results were obtained in all genetic models of CALCR rs1801197." (PMID 31626518, 2019).
adenoma (1 paper, 2025). A neoplasm arising from the epithelium. "Several interactions only occurred in specific locations, such as signalling pathways of CALCR, RANKL and TWEAK in the submucosa, GDNF, GDF, IL12, CD30 and CD137 signalling pathways in the adenoma, and PD‐L1, GP1BA, RESISTIN and SPP1 signalling pathways in tumour." (PMID 39934971, 2025).
Arrhythmia (1 paper, 2026). Any cardiac rhythm other than the normal sinus rhythm. "Selective disruption of miR-31–5p/CALCR interaction reverses atrial fibrosis and arrhythmia in vivo." (PMID 41542044, 2026).
breast tumors (1 paper, 2022). "Analysis of primary breast tumors revealed that miR-489 expression positively correlated with the expression of CALCR, ESR1, and ER-responsive genes such as progesterone receptor (PGR), suggesting that miR-489 expression may be regulated by estrogen signaling." (PMID 35897675, 2022).
endometriosis (1 paper, 2024). The growth of functional endometrial tissue in anatomic sites outside the uterine body. "Interestingly, the CALCR and BTLA pathways are present in both endometriosis conditions and CCC but not in healthy tissue, indicating a dysregulation in the calcium pathway and immune checkpoint, respectively." (PMID 39149248, 2024).